PLAGL1 (PLAG1 like zinc finger 1)
Description:
Acts as a transcriptional activator. Involved in the transcriptional regulation of type 1 receptor for pituitary adenylate cyclase-activating polypeptide.
Synonyms: LOT1; ZAC; ZAC1
Tractability: PROTAC: ubiquitination databases record sites on it.
Gene: Protein-coding gene on chromosome 6 (143,940,300 to 144,064,714, reverse strand). Ensembl gene ENSG00000118495.
Subcellular location: Nucleus
Subcellular location (Human Protein Atlas): Nuclear bodies; Golgi apparatus; Vesicles
Gene Ontology:
Molecular function: DNA binding; DNA-binding transcription activator activity, RNA polymerase II-specific; protein binding; RNA polymerase II transcription regulatory region sequence-specific DNA binding; DNA-binding transcription repressor activity, RNA polymerase II-specific; RNA polymerase II cis-regulatory region sequence-specific DNA binding
Biological process: positive regulation of transcription by RNA polymerase II; apoptotic process; negative regulation of transcription by RNA polymerase II; regulation of cell cycle; regulation of cytokine production; regulation of immune system process
Cellular component: nuclear body; nucleoplasm; nucleus
Genetic constraint (gnomAD): Loss-of-function variants: 1 observed, 4.64 expected, observed/expected ratio (o/e) 0.22, 90% interval 0.075 to 1.02. That is too few expected variants to judge how well the gene tolerates losing a copy. Missense variants: 463 observed, 588.13 expected, observed/expected ratio (o/e) 0.79, 90% interval 0.73 to 0.85. Synonymous variants: 239 observed, 243.99 expected, observed/expected ratio (o/e) 0.98, 90% interval 0.88 to 1.09.
Homologues: Orthologues: chimpanzee PLAGL1 (99% identical), macaque PLAGL1 (99% identical), pig PLAGL1 (92% identical), dog PLAGL1 (91% identical), rabbit PLAGL1 (80% identical), guinea pig PLAGL1 (78% identical), mouse Plagl1 (71% identical), rat Plagl1 (71% identical), zebrafish plagl2 (46% identical), zebrafish plagx (29% identical), Drosophila melanogaster hb (12% identical), Drosophila melanogaster CG12391 (12% identical), and 2 more. Paralogues in human: PLAG1 (46% identical), PLAGL2 (44% identical), PEG3 (15% identical), ZNF518A (12% identical), ZSCAN29 (12% identical), REST (11% identical), ZNF518B (11% identical), ZKSCAN2 (11% identical), ZNF274 (11% identical), ZBTB35 (11% identical), ZNF202 (11% identical), ZNF770 (11% identical), and 17 more.
Diseases named in the same sentence as PLAGL1 in open-access papers:
PLAGL1 is named in the same sentence as 94 diseases in open-access papers, as found by Europe PMC text mining. Sharing a sentence is not in itself a finding about the gene and the disease. The quoted sentences say what the papers report.
transient neonatal diabetes mellitus (19 papers, 2009 to 2025). Transient neonatal diabetes mellitus (TNDM) is a genetically heterogeneous form of neonatal diabetes (NDM) characterized by hyperglycemia presenting in the neonatal period that remits during infancy but recurs in later life in most patients. "PLAGL1 is associated with transient neonatal diabetes mellitus and paternal uniparental disomy of chromosome 6, and NPSR1 is associated with asthma-related traits." (PMID 38291454, 2024). "Transient neonatal diabetes mellitus 1 is caused by overexpression of the maternally imprinted genes PLAGL1 and HYMAI on chromosome 6q24." (PMID 27075368, 2016). "Transient neonatal diabetes mellitus 1 (TNDM1) is an imprinting disorder caused by overexpression of the maternally imprinted genes PLAGL1 and HYMAI on chromosome 6q24." (PMID 27075368, 2016). "The Plagl1 gene encodes a growth suppressor protein that is related to developmental disorders such as growth retardation and transient neonatal diabetes mellitus (TNDM)." (PMID 19630995, 2009). "In humans, the loss of PLAGL1 expression causes ‘transient neonatal diabetes mellitus’ (TNDM, OMIM 601410), an imprinting disorder characterised by intra-uterine growth restriction, similarly to what is observed in Silver-Russell Syndrome (SRS), an ID most often caused by reduced IGF2 expression." (PMID 37686455, 2023). "This locus, and overexpression of PLAGL1 specifically, has been associated with transient neonatal diabetes mellitus (TNDM) possibly by reducing insulin secretion." (PMID 30082726, 2018). "Perturbation of PLAGL1's activating role is causally involved in transient neonatal diabetes mellitus (TNDM)." (PMID 26842569, 2016). "Approximately half of transient neonatal diabetes mellitus (TNDM) patients with methylation disturbance at PLAGL1 have biallelic pathogenic variants in ZFP57, and have MLID involving LOM at PLAGL1, GRB10, and PEG3." (PMID 39090763, 2024). "PLAGL1 encodes a C2H2 zinc finger protein that functions as a suppressor of cell growth and is a strong candidate for transient neonatal diabetes mellitus (TNDM1; MIM#601410)." (PMID 35246208, 2022). "Over-expression of the human PLAGL1 gene is thought to be responsible for Transient Neonatal Diabetes Mellitus (TNDM), a genetic disease characterised by severe intrauterine growth restriction and insulin dependence in neonates." (PMID 22723905, 2012). "It was previously demonstrated that transient neonatal diabetes mellitus is associated with overexpression of PLAGL1 gene, although our study did not reveal many changes in GD patients." (PMID 35454338, 2022). "Alterations in this gene locus, such as paternal duplication or loss of methylation at the PLAGL1 DMR, precipitate transient neonatal diabetes mellitus (TNDM) due to heightened PLAGL1 expression." (PMID 39365284, 2024). "On the other hand, paternal duplication of the PLAGL1 locus is responsible for transient neonatal diabetes mellitus (TNDM) which has characteristics such as intrauterine growth retardation and hyperglycemia due to lack of normal insulin secretion." (PMID 33918057, 2021). "PLAGL1 is a paternally expressed imprinted gene on chromosome 6q24, a region where paternal duplication or loss of methylation at the PLAGL1 DMR causes transient neonatal diabetes mellitus (TNDM) locus owing to PLAGL1 overexpression." (PMID 33986727, 2021). "BWS9 who showed additional LoM of PLAGL1:alt-TSS-DMR in 6q24.2, implicated in the etiology of transient neonatal diabetes mellitus-1 (OMIM #601410), did not exhibit hyperglycemia until 9.3 years of age." (PMID 37594968, 2023). "In 2005 for the first time there were reported two patients with MLID presented transient neonatal diabetes mellitus (TNDM) and hypomethylation of both iDMRs of KCNQ1OT1 gene and of PLAGL1, an antiapoptotic gene located at chromosome 6q24." (PMID 33101381, 2020).
diabetes (14 papers, 2009 to 2025). "Similar to GLIS3, the PLAGL1 gene encodes for a zinc finger protein associated with diabetes and has been nominated as a tumor suppressor." (PMID 34715892, 2021). "Among these interactors, EIF2AK3, GLIS3, IER3IP1, and PLAGL1 are linked to Diabetes mellitus in Swiss-Prot." (PMID 34715892, 2021). "PLAGL1 is a zinc finger protein associated with cell growth suppression and with transient neonatal diabetes mellitus." (PMID 30246009, 2018). "In mice, paternally expressed Plagl1 is implicated in transient neonatal diabetes when overexpressed." (PMID 26115033, 2016). "Indeed, genetic imprinting on chromosome region 6q24 PLAGL1-HYMAI is associated with transient neonatal diabetes, a rare form of diabetes whereby an increased dosage at the chromosome 6q24 region leads to impaired glucose regulation and diabetes." (PMID 34201206, 2021). "Overexpression of Plagl1 during fetal development causes transient neonatal diabetes mellitus." (PMID 32716923, 2020). "Differential methylation of the zinc finger protein gene pleomorphic adenoma gene 1 (PLAGL1) was found in diabetes and cancer and was shown to modulate the expression levels of this gene." (PMID 24963031, 2014). "The use of MS-MLPA is essential for the diagnosis of 6q24-TNDM, identifying paternal UPD6, paternal 6q24 duplications, or isolated maternal hypomethylation of the PLAGL1/HYMAI locus in patients with diabetes diagnosed in the first weeks of life and other coexisting disorders." (PMID 41153775, 2025). "For example, patients with LoM at the PLAGL1 locus require monitoring for early-onset diabetes." (PMID 37594968, 2023).
neuroepithelial tumors (10 papers, 2021 to 2025). "Neuroepithelial tumors with fusion of PLAGL1 or amplification of PLAGL1/PLAGL2 have recently been described often with ependymoma-like or embryonal histology respectively." (PMID 39228008, 2024). "Because of this morphological spectrum, the terminology “neuroepithelial tumor, with PLAGL1-fusion” (NET-PLAGL1) was preferred while awaiting additional studies." (PMID 38581034, 2024). "This entity has been defined by a distinct DNA‐methylation profile, and is notably different from neuroepithelial tumors, PLAGL1‐fused, which present histopathological similarities to ependymomas and harbor unique fusions of the PLAGL1 gene." (PMID 37349135, 2023). "PLAGL1/2 amplifications have been reported in a subgroup of embryonal tumors, whereas PLAGL1 fusions have been described in ependymoma-like neuroepithelial tumor (NET)." (PMID 37870637, 2023). "PLAGL1 fusion-positive neuroepithelial tumors should thus be included into upcoming classifications of brain tumors." (PMID 34355256, 2021). "The 4 emerging neuroepithelial tumors were diagnosed based on detection of the CIC, PATZ1, and PLAGL1 fusion genes." (PMID 40980447, 2025). "A novel methylation class, “neuroepithelial tumor, with PLAGL1 fusion” (NET-PLAGL1), has recently been described, based on epigenetic features, as a supratentorial pediatric brain tumor with recurrent histopathological features suggesting an ependymal differentiation." (PMID 38581034, 2024).
ovarian carcinoma (8 papers, 2011 to 2023). A malignant neoplasm originating from the surface ovarian epithelium. "LOT1(PLAGL1/ZAC1) is known to possess anti-proliferative effects and is frequently silenced in ovarian cancer and breast cancer." (PMID 25079112, 2014). "Among top 20 ranked miRNA-mRNA interaction pairs, the roles of four targets including PLAGL1, MTUS1, MEF and IFNGR1 have been reported in ovarian cancer." (PMID 25079112, 2014). "We therefore attempted to illustrate these genomic and epigenetic sample irregularities (such as observed in PLAGL1, CCNE1 and PIAS3) for many of the known ovarian cancer genes." (PMID 22174824, 2011). "Other genes that were strongly increased in the ovarian cancer cell lines were HIPK2 and PLAGL1." (PMID 31344863, 2019). "The maternally imprinted PLAGL1 is expressed in normal tissues and downregulated in various tumors, such as breast cancer, ovarian cancer, nonfunctioning pituitary tumors, basal cell carcinomas, head and neck squamous cell carcinoma, and diffuse large B-cell lymphoma." (PMID 36437415, 2023).
breast carcinoma (7 papers, 2015 to 2025). "Prior studies have shown that PLAGL1 is a tumor suppressor gene encoding an inducer of apoptosis and cell cycle arrest in various cancers (eg, breast cancer, hepatoma, and colon cancer)." (PMID 33392508, 2020). "DCIS breast cancer risk increased with higher KvDMR-ICR2 methylation (OR 1.395; 95 % CI 1.190, 1.635; p < 0.001) and lower PLAGL1/ZAC1 methylation (OR 0.905; 95 % CI 0.833, 0.982; p = 0.017)." (PMID 26347357, 2015). "This analysis indicates that the predicted PTB-related genes including ICAM1, CRHBP, PLAGL1, EGR2, CNTLN, and DKK1 play an important role in preforming biological activities associated with PTB, infant disease, and possibly breast cancer, due to the gestational age-induced." (PMID 36788602, 2023). "By joint analysis of gene expression data from previous studies, we constructed interrelationships of mainly CRHBP, ICAM1, PLAGL1, DNMT1, CNTLN, DKK1, and EGR2 with preterm birth, infant disease, and breast cancer." (PMID 36788602, 2023). "PLAGL1 has been reported as a possible epigenetically regulated tumor suppressor gene, and NR0B1 (also known as DAX-1) has been repeatedly indicated as a potential target for anticancer therapy in patients with breast cancer." (PMID 40724805, 2025). "Conversely, underexpression of PLAGL1 and GCNT4 were found in all three types of breast cancer." (PMID 36788602, 2023).
neonatal diabetes mellitus (7 papers, 2018 to 2025). Neonatal diabetes mellitus presents as hyperglycemia, failure to thrive and, in some cases, dehydration and ketoacidosis which may be severe with coma, in a child within the first months of life. "PLAGL1 is a transcription factor that, when imprinted incorrectly, leads to beta cell loss and transient neonatal diabetes mellitus." (PMID 41256547, 2025). "Furthermore, loss of DNA methylation at this locus results in transient neonatal diabetes mellitus which is postulated to be caused by an increase in expression of PLAGL1." (PMID 30021660, 2018). "Previous studies have identified biallelic expression of Plagl1 from an alternate promoter P2 situated 30 kb upstream to the P1 promoter (site of imprinting) in patients with transient neonatal diabetic mellitus (TNDM)." (PMID 36751888, 2023).
brain tumor (6 papers, 2021 to 2025). "While PLAG1 and PLAGL2 have been described as proto-oncogenes, PLAGL1 seems to act in a context dependent manner either as a tumor suppressor gene or, as recently described by us and others, as a proto-oncogene in the brain tumor context." (PMID 40751809, 2025). "In the brain tumor context, our evidence supports an oncogenic role also for PLAGL1, which is further substantiated by the recent discovery of recurrent PLAGL1 fusions in a subset of pediatric-type supratentorial neuroepithelial tumors." (PMID 36437415, 2023). "Our findings further support that in a brain tumor context, both PLAGL1 and PLAGL2 likely act as oncogenes, whose amplification and resultant overexpression drive tumor development." (PMID 36437415, 2023). "More recent studies provide evidence for its oncogenic function in brain tumors with overexpression of PLAGL1 being involved in tumorigenesis of glioblastoma and interaction of PLAGL family transcription factors in ZFTA:RELA-fused supratentorial ependymoma." (PMID 34355256, 2021). "In summary, we provide evidence for a novel group of supratentorial brain tumors and identify PLAGL1 as a putative relevant driver in this entity." (PMID 34355256, 2021). "However, much evidence suggests that PLAGL1 might work as an oncogenic factor in many brain tumors." (PMID 36600208, 2023). "Overexpression of this specific gene set seems to be uniquely characteristic of PLAGL1/2-amplified tumors, as we do not find this combination, and especially not CYP2W1 expression, in any of the other investigated brain tumor types." (PMID 40751809, 2025).
ependymoma (6 papers, 2021 to 2025). A WHO grade II, slow growing tumor of children and young adults, usually located intraventricularly. "In the central nervous system (CNS), most neoplasms presenting a PLAGL1 fusion have initially been diagnosed as ependymomas in the supratentorial area of children and young adults (median age of 6.2 years old, ranging from 0 to 30)." (PMID 38581034, 2024). "Cases of ependymoma-like NET with PLAGL1 fusions were distinct from ours in terms of location (all NET were supratentorial), histopathology (NET present frequent ependymal features) and immunohistochemistry (constant expression of GFAP in NET)." (PMID 37870637, 2023). "Quantification of mRNA expression revealed that the PLAGL1 gene itself was more highly expressed in tumors within the novel group than in ZFTA:RELA-fused ependymoma (adjusted p = 1.22e − 14)." (PMID 34355256, 2021). "However, in a very recent report, a PLAGL1:EWSR1 fusion was described in a supratentorial ependymoma of a six-year-old child." (PMID 34355256, 2021). "This cohort of supratentorial PLAGL1-fused tumors highlights: 1/ the ependymal cell origin of this new neoplastic entity; 2/ benefit of looking for a PLAGL1 fusion in supratentorial cases of non-ZFTA/non-YAP1 ependymomas; and 3/ the usefulness of PLAGL1 FISH." (PMID 38581034, 2024). "The current work showed a high proportion (60% of cases) of PLAGL1 alterations discovered in the selected population of supratentorial ependymomas, non-ZFTA/non-YAP1 fused and supratentorial subependymomas of the young." (PMID 38581034, 2024). "Herein, we present a detailed series of nine cases of PLAGL1-fused supratentorial tumors, reclassified from a series of supratentorial ependymomas, non-ZFTA/non-YAP1 fusion-positive and subependymomas of the young." (PMID 38581034, 2024).
Obesity (6 papers, 2016 to 2023). Accumulation of substantial excess body fat. "Furthermore, PLAGL1 may be implicated in lipid metabolism and obesity through its effect on IDI1, PNPLA1, JAK3, and RAB37 expression." (PMID 30082726, 2018). "Finally, it has recently been shown that KAP1 haploinsufficiency triggers bistable obesity in mice, where the obesity state is characterized by a reduced expression of an imprinted gene network, including Nnat, Plagl1, and Peg367." (PMID 31000713, 2019). "PLAGL1 is thought to be an imprint control region; however, the implications of this in relation to a potential role in the risk of early obesity are not yet clear." (PMID 29988473, 2018). "PLAGL1, MEST, NNAT, and PEG10 have been associated with obesity or weight in previous literature." (PMID 29988473, 2018).
embryonal tumors (5 papers, 2023 to 2025). "While not formally recognized by the WHO CNS5 criteria, patients with CNS embryonal tumors and PLAGL1 rearrangements have been described." (PMID 38639853, 2024). "The novel embryonal tumor with amplification of the PLAGL1/2 genes mainly concerns children (85% of reported cases, ranging from 0 to 36 years old) and may be located all along the neuraxis (mostly hemispheric but also infratentorial and ventricular)." (PMID 37870637, 2023). "Three cases out of 31 (9.7%) of DNA-methylation based embryonal tumors with PLAGL1/2 did not harbor any amplifications of these genes, and to our knowledge, PLAG1 fusions were not explored." (PMID 37870637, 2023). "A subset (MEST, PLAGL1, PEG3, DLK1, IGF2) showed elevated expression in various embryonal cancers, especially rhabdomyosarcoma, as compared to non-embryonal cancers and normal tissues." (PMID 36437415, 2023).